RARA (retinoic acid receptor alpha)
Diseases named in the same sentence as RARA in open-access papers (continued):
Sharing a sentence is not in itself a finding about the gene and the disease.
chronic myeloid leukemia (11 papers, 2009 to 2024). "Furthermore, the first generation BCR-ABL1 TKI for chronic myeloid leukemia (CML) imatinib (STI571, Gleevec) potentiated pharmacological activity of retinoic acid in APL cells and affected degradation of RARα and PML-RARα." (PMID 26065685, 2015).
gastric cancer (11 papers, 2003 to 2025). A primary or metastatic malignant neoplasm involving the stomach. "In fact, high levels of RARα, RARβ, RXRα and RXRβ are associated with unfavorable prognostic clinical and pathological characteristics of gastric cancer, such as stage-IV and “de novo” metastatic disease." (PMID 39323992, 2024). "In gastric cancer, high expression levels of RARα/RARβ/RARγ/RXRβ transcripts are associated with poor clinical and molecular characteristics as well as with reduced overall-survival." (PMID 39323992, 2024). "Finally, we established associations of the RARα, RARβ, RARγ and RXRβ levels with a detrimental effect on the overall-survival of gastric cancer patients." (PMID 39323992, 2024). "The GEPIA database was then utilized to further assess these TFs, highlighting HNF4A and RARA as highly expressed in stomach cancer (STAD), with subsequent analyses indicating a significant positive correlation between HNF4A and TYMS." (PMID 41326348, 2025). "For example, RARA was found among the pro-differentiation genes recurrently hypermethylated in EBV-positive gastric cancers." (PMID 41280003, 2025). "The work supports the idea that RARα, RARβ, RARγ and RXRβ represent potential prognostic markers and actionable therapeutic targets in the context of the personalized treatment of gastric cancer." (PMID 39323992, 2024). "In this study, we determine the RNA expression of the six isoforms of Retinoic-Acid-Receptors (RARα/RARβ/RARγ/RXRα/RXRβ/RXRγ) in view of their potential use as gastric cancer progression markers and/or therapeutic targets." (PMID 39323992, 2024). "Taken together, our data support the idea that the tumor levels of RARα, RARβ, RARγ and RXRβ mRNAs are potential determinants of a low overall-survival rate in gastric cancer." (PMID 39323992, 2024). "Our data are consistent with the idea that RARα, RARβ, RARγ and RXRβ represent potential prognostic markers and therapeutic targets of gastric cancer." (PMID 39323992, 2024). "The results of the RAR-GASTRIC study demonstrate that gastric cancer specimens contain significant amounts of RARα/RARβ/RXRα/RXRβ mRNAs." (PMID 39323992, 2024). "In this single-institution/retrospective clinical and translational study (RAR-GASTRIC), we define the expression of RARα, RARβ, RARγ, RXRα, RXRβ and RXRγ in stomach tumors with the use of archival tissue samples obtained from gastric cancer patients." (PMID 39323992, 2024). "To identify the RAR isoform(s) underlying the anti-proliferative action of the retinoid, initially, we evaluated the constitutive expression of RARα, RARβ, RARγ, RXRα, RXRβ and RXRγ mRNAs in our gastric-cancer cell-lines." (PMID 37951921, 2023). "In fact, combination of ERBB2 antagonist or RARA agonist was reported to be effective synergistic regimens for ERBB2 positive gastric cancer." (PMID 33897415, 2021). "IL-1β is involved in the positive feedback loop of IL-1β/Akt/retinoic acid receptor α (RARα) signaling, and thereby transmits the oncogenic property of RARα in gastric carcinoma." (PMID 30042333, 2018). "In a previous report on RARs' and RXRs' Northern mRNA expression level of gastric cancer cell lines, enhanced expression of RARα/RARγ was observed in SC-M1 cells and enhanced RARβ level was found in TSGH cells." (PMID 12671705, 2003). "Finally, we observe a worse overall-survival in gastric cancer patients characterized by high RARα/RARβ/RARγ/RXRβ mRNA levels." (PMID 39323992, 2024). "PML/RARα is known to enhance STAT3 expression, and STAT3 has been reported to epigenetically silence NR4A3 expression in gastric cancer." (PMID 36040481, 2022). "However, the role and the mechanism of RARα in gastric carcinoma (GC) were unknown." (PMID 28035062, 2017). "Based on our results, it is reasonable to assume that high expression levels of RARα, RARβ, RXRα and RXRβ have a negative impact on gastric cancer patients’ overall-survival." (PMID 39323992, 2024).
gastric cancer (continued). "Furthermore, only a few of the top twenty transcription factors identified are expressed among the gastric cancer cell lines and do not appear to be greatly affected by DCB treatment, including RARA, ATF1, THRA, and MEF2A." (PMID 41280003, 2025).
hepatocellular carcinoma (10 papers, 1998 to 2025). A malignant tumor that arises from hepatocytes. "Mice expressing liver-specific RARα dominant negative protein exhibited microalveolar steatosis at 4 months, decreased mitochondrial β-oxidized fatty acids, and developed hepatocellular carcinoma and hepatic adenoma at 1 month." (PMID 38699158, 2024). "HOXB7 and RARA are schizophrenic genes with different gene expressions, modulated through the retinoid signaling pathway by the hepatocellular carcinoma over-expression gene PARP1." (PMID 24564241, 2013). "RARα has been identified as highly expressed in hepatocellular carcinoma (HCC), and is possibly responsible for abnormal growth of HCC." (PMID 28035062, 2017). "In the present study, we sought to identify the factors involved in the RARα-mediated transcriptional regulation of the tumor suppressor gene and the tissue factor pathway inhibitor 2 (TFPI2) in hepatocellular carcinoma (HCC)." (PMID 29757260, 2018). "It was found that Vitamin A, retinoid acid and a few other immune response agents modulated by RARA and LCK genes may be potential treatments for both schizophrenia and hepatocellular carcinoma." (PMID 24564241, 2013).
myelodysplastic syndrome (10 papers, 2010 to 2025). A clonal hematopoietic disorder characterized by dysplasia and ineffective hematopoiesis in one or more of the hematopoietic cell lines. "In acute promyelocytic leukaemia (APL), anaplastic large cell lymphoma (ALCL), myelodysplastic syndrome (MDS) and acute myeloid leukaemia (AML), NPM is reported to form fusion proteins with ALK, RARα, and MLF15." (PMID 27619510, 2016). "Beyond DS-ALL, NRAS p.G13D has been recurrently described in RARA-negative acute promyelocytic-like leukemia with concomitant myelodysplastic syndrome, in lupus nephritis through aberrant RAS-MAPK signaling, in colorectal cancer, and in histiocytosis syndromes." (PMID 41020826, 2025).
Alzheimer disease (9 papers, 2008 to 2024). A progressive, neurodegenerative disease characterized by loss of function and death of nerve cells in several areas of the brain leading to loss of cognitive function such as memory and language. "Selective RARα agonists have also been shown to prevent neuronal cell death caused by amyloid-β and, when administered orally, can prevent amyloid-β production and Alzheimer’s disease progression in a mouse model." (PMID 29288071, 2018). "In animal models of Alzheimer’s disease, RARα agonists have been demonstrated to decrease congenital neuroinflammation, enhance phagocytosis, and decrease neuropathology." (PMID 36768908, 2023). "The use of CMA activators (such as the RARA antagonist AR7) to improve proteostasis in models of Alzheimer’s disease provides promising preclinical data that CMA activation could be therapeutically beneficial in neurodegenerative disorders." (PMID 39687864, 2024). "In addition to the direct role of ATRA on tau tangle formation, it can also indirectly inhibit tau hyperphosphorylation in Alzheimer’s disease by the RARA/glycogen synthase kinase 3 beta (GSK-3β) pathway." (PMID 38572181, 2024). "Thus selective RARα agonists have the therapeutic potential for the treatment of cancer, dermatological diseases, Alzheimer’s disease and immunological disorders." (PMID 29288071, 2018). "One mechanistic role for RARα signaling in preventing amyloid-β accumulation at the onset of Alzheimer's disease is by increasing Notch related α-secretase activity via a direct induction of ADAM10, and Alzheimer's-like defects are indeed suppressed by RARα agonists in a transgenic mouse model." (PMID 22396766, 2012).
breast tumors (9 papers, 2011 to 2024). "Its antiproliferative actions depends upon breast tumor subtype and distinct genetic characteristics (e.g., RARA amplification, NOTCH1 activating deletion)." (PMID 38360674, 2024). "In particular, ATRA is reported to induce the formation of adherent junctions and the reorganization of tight junctions by activating a RARα-dependent epithelial differentiation program in sensitive breast tumor cells." (PMID 30497437, 2018). "RARα is consistently present in the nucleus in breast tumors and its expression levels correlate with that of the proliferation marker, ki-67." (PMID 21299862, 2011). "cDNA prepared from the total RNA of MCF-7 cells as well as five breast tumors and normal human tissue controls (breast, spleen, thymus and peripheral blood leukocytes) were analyzed for RARα isoform expression by PCR." (PMID 21299862, 2011). "SKBR3 cells are characterized by co-amplification of the genes coding for HER2 and the nuclear retinoic acid receptor, RARα, and they are representative of a novel subgroup of HER2+ breast tumors with selective sensitivity to simultaneous targeting of RARα with ATRA and HER2 with Lapatinib." (PMID 25961594, 2015). "According to the hormone receptor status of breast tumor cells, ER-positive breast cancer has been found to have relatively high levels of RARα and to be sensitive to retinoids, whereas ER-negative tumors have low levels of RARα and were found to be resistant to retinoids." (PMID 34579037, 2021). "Preclinical and clinical data indicate that RARα levels determine the response to retinoids, and overexpression of RARα and HER2 has been reported in human breast tumors." (PMID 29899874, 2018).
myeloid neoplasm (8 papers, 2016 to 2024). Proliferation of myeloid cells originating from a primitive stem cell. "FIP1L1::RARA is a rare alternative fusion type associated with myeloid neoplasm composed of 426 amino acids (AA) from the N terminus of FIP1L1 and 403 AA from the C terminus of RARA." (PMID 36776354, 2022). "Obvious transcriptomic differences between APL with FIP1L1::RARA and myeloid neoplasms were identified." (PMID 36776354, 2022). "Secondly, the number of APL patients with FIP1L1::RARA and other myeloid neoplasms is extremely limited, and the credibility of the results is limited." (PMID 36776354, 2022). "Several patients with FIP1L1::RARA were diagnosed as other myeloid neoplasms." (PMID 36776354, 2022). "RNA-seq may be a new diagnostic method when RARA rearrangements are failed to be identified by conventional methods, because of the obvious transcriptomic difference between APL with FIP1L1::RARA and myeloid neoplasms." (PMID 36776354, 2022).
ovarian carcinoma (8 papers, 2007 to 2023). A malignant neoplasm originating from the surface ovarian epithelium. "We have previously demonstrated localization of RARα in tumor infiltrating mononuclear cells in fibroblasts and in vascular endothelial cells from ovarian cancer specimens." (PMID 23675020, 2007). "We then performed the Chromatin immunoprecipitation (ChIP) assay using the anti-RARα antibody to determine whether RARα can bind to this region in ovarian cancer cells." (PMID 37429899, 2023). "However, of the four TFs (PITX1, RARA, FOXF1/A1, and BHLHE41/40) that matched the binding motifs in DEG promoters, only one, FOXA1, has previously been implicated in ovarian cancer specifically." (PMID 34215221, 2021). "Despite several papers that mentioned a special role of RXRα receptor in resistance mechanisms, maximum resistance to retinoic acid was shown in ovarian cancer cell lines with downregulation of both RARα and RXRα in contrast to cell lines with reduced levels of either RARα alone or RXRα alone." (PMID 29301374, 2018). "Response to ATRA treatment in the ovarian cancer cell lines did not correlate with expression of ANXA2, S100A10 or retinoic acid receptor alpha (RARA) as all cell lines exhibited similar gene expression levels." (PMID 30621740, 2019). "Although is not clear why ovarian cancer cell lines are resistant to ATRA treatment, our study suggests that resistance to ATRA treatment is not dependent on RARA, ANXA2 or S100A10 expression as all of the serous ovarian cancer cell lines expressed similar mRNA levels of these genes." (PMID 30621740, 2019).
vitamin A deficiency (7 papers, 2011 to 2025). Deficiency of vitamin A due to malnutrition, malabsorption, or dietary lack. "Vitamin A deficiency reduced the levels of hepatic Rarα mRNA (1.2-fold, p = 0.001), while the atRA diet up-regulated hepatic Rarα mRNA, in relation to the control rats." (PMID 27551308, 2016). "Vitamin A deficiency affects pIgR and RARα expression levels in vivo and in vitro." (PMID 37180172, 2023). "Findings from this study suggest that cigarette smoke-induced lung retinoic acid depletion may involve two independent pathways, RARα- and RARβ-mediated, responsible for the increased cancer risk associated with cigarette smoke-induced vitamin A deficiency." (PMID 26462767, 2015). "Additionally, vitamin A deficiency is linked with an increased expression of RARα, in contrast with the decreased expression of RARβ." (PMID 26462767, 2015). "RARα/γ compound mutants show a hindbrain phenotype similar to that seen in vitamin A deficiency, whereas the RARα/β compound null mutants present a less severe phenotype, indicating that RARα and RARγ play an important role at early stages of hindbrain patterning." (PMID 22254103, 2011). "Vitamin A deficiency (VAD) increased hepatic Bmp6 and Hfe2 mRNA levels and down-regulated hepatic Hamp, Smad7, Rarα, and intestinal Fpn1 mRNA levels compared with the control." (PMID 27551308, 2016). "Deletion of the whole RARα led to death of >90% of the homozygotes before the age of 2 months, but the mice failed to display any of the vitamin A deficiency-associated lesions other than testis degeneration." (PMID 37082619, 2023).
colon carcinoma (6 papers, 2013 to 2022). "In conclusion, the present study represents a comprehensive analysis of the global alterations of ATG genes in a broad range of cancer types, with emphasis on the roles of EGFR and RARA in colon cancer cells." (PMID 31896739, 2020). "Moreover, we found that RARα, RXRα, and RXRβ showed higher expression, while RARβ showed lower expression in colon carcinoma cells (poorly differentiated), the normal colon (highly differentiated) being the control (data not shown)." (PMID 25881300, 2015). "Thus, ATRA-enhanced MUC-2 expression in SW480 colon cancer cells is at least partly mediated through CysLT2R and RARα signaling." (PMID 23829413, 2013). "In the current study, we show that ATRA’s ability to induce MUC-2 expression in SW480 colon cancer cells might also involve CysLT2R signaling, as the effect can be reduced by either a CysLT2R inhibitor or by RARα siRNA alone or a combination of RARα and RARβ siRNA." (PMID 23829413, 2013). "RARB is also found to be downregulated in several types of cancer, including colon cancer, and it has been demonstrated that silencing of RARB correlates with impaired RARα-signaling." (PMID 35275975, 2022). "EGFR contributed to 5-FU resistance in colon cancer cells through autophagy induction, and EGFR overexpression in 5-FU resistant colon cancer was regulated by RARA." (PMID 31896739, 2020). "The authors found that the compounds of LWDHW may play an important role in esophagitis and colon cancer by regulating the expression of C-C chemokine receptor 2 (CCR2), estrogen receptor 1 (ESR1), peroxisome proliferator-activated receptor gamma (PPARG), and retinoic acid receptor alpha (RARA)." (PMID 30846939, 2019).
embryonal carcinoma (6 papers, 2009 to 2025). A non-seminomatous malignant germ cell tumor characterized by the presence of large germ cells with abundant cytoplasm resembling epithelial cells, geographic necrosis, high mitotic activity, and pseudoglandular and pseudopapillary structures formation. "Truncated RARα caused resistance to retinoids in an embryonal carcinoma cell line whereas epithelial cells with different types of truncated RARα mutants were more sensitive to treatment with retinoic acid." (PMID 29301374, 2018). "Studies have examined the effect of treating P19 and F9 embryonal carcinoma cells with a combination of the synthetic RARα- and RARγ-selective agonists Am80 and CD666, respectively." (PMID 37082619, 2023). "Our results are in good accordance with data from Glozak and Rogers showing that in P19 embryonal carcinoma cells RA/BMP-4 induced apoptosis is mediated through the specific activation of RARα." (PMID 26173116, 2015). "The hypothesis that in vitro and in vivo pathways are comparable is supported by significant up-regulation of RARα and RARβ mRNA, but rapid down-regulation of RARγ and RXRγ mRNA during RA-induced neuronal differentiation of mouse embryonal carcinoma cells." (PMID 19642999, 2009). "Studies that made use of selective RARα, β, and γ, revealed that RARγ was the functionally dominant RAR that mediates the development of stiatopallal-like neurons from embryonal carcinoma cells." (PMID 40362593, 2025). "We previously demonstrated in a mouse embryonic carcinoma cell model that anendogenous dominant negative RARα mutant, lacking part of the E domainharboring the RA-binding domain, induced concerted epigenetic repression of bothRARβ2 and CYP26A1, encoding for aRA hydrolase involved in RA catabolism." (PMID 19173001, 2009).
glioma (6 papers, 2015 to 2023). A benign or malignant brain and spinal cord tumor that arises from glial cells (astrocytes, oligodendrocytes, ependymal cells). "Sumo1 modification of RARA signals additional posttranslational modification as part of the proteasomal pathway, but this pathway is disrupted in glioma." (PMID 31700049, 2019). "Glioma cells express sumoylated and high molecular weight RARA and RXRA proteins that have accumulated even before retinoic acid treatment." (PMID 31700049, 2019). "The glioma stem-like cells express high molecular weight forms of RARA and RXRA that fail to be recognized by the proteasome and lack transcriptional activity." (PMID 31700049, 2019). "Additionally, ATRA has a pro-proliferative and pro-survival effect on stem-like glioma cells mediated by RARα and RARγ." (PMID 36010607, 2022). "Perhaps disruption to the proteasomal processing of RARA was missed in glioma because the receptor-independent effects of RA were unknown at that time." (PMID 31700049, 2019). "We hypothesized that sumoylation may have a role in regulating the proteasomal degradation of RARA during protein turnover of both normal neural stem cells and glioma stem-like cells." (PMID 31700049, 2019). "Therefore, we hypothesize that the inherent resistance to retinoic acid in glioma cells may be due to a block in retinoid receptor degradation pathway that occurs after sumo modification, but before the RARA and RXRA proteins are delivered to the proteasome." (PMID 31700049, 2019). "Therefore, normal and glioma RARA are sumoylated by the Sumo1 peptide." (PMID 31700049, 2019). "We found that RARA and RXRA protein turnover is blocked in glioma stem-like cells and RARA transcriptional activity is disrupted." (PMID 31700049, 2019). "Furthermore, stem-like glioma cells, isolated from primary GBM, expressed RARα." (PMID 36010607, 2022).